NF2 (NF2, moesin-ezrin-radixin like (MERLIN) tumor suppressor)
Diseases named in the same sentence as NF2 in open-access papers (continued):
Sharing a sentence is not in itself a finding about the gene and the disease.
meningioma (continued). "Neurofibromatosis type 2 or NF2 is a devastating autosomal dominant genetic syndrome characterized by mutations of the NF2 tumor suppressor gene leading to an increased risk for central nervous system tumors including bilateral VS, meningiomas and ependymomas." (PMID 30760974, 2019). "Because subtotal resection is the most common indication for postoperative RT, and tumors with NF2 mutations received less adjuvant RT, it is also possible that NF2 mutation-driven meningiomas are easier to resect, due to surgical access of their specific intracranial location." (PMID 31191822, 2019). "According to the literature, TRAF7 is the most often affected gene in non-NF2 mutated meningiomas." (PMID 31470906, 2019). "Indeed, the most significant, and often the only, SCNA in meningioma is chromosome 22 monosomy, which is present in ~56% of cases and leads to loss of the genomic locus containing NF2 (22q12.2)." (PMID 31970090, 2019). "As such, drugs targeting the mTOR hold promise for treatment of NF2-mutated meningiomas." (PMID 31970090, 2019). "This may also indicate that meningiomas driven by NF2 mutations are slower growing and only become symptomatic when they become very large and cause mass effect on surrounding structures." (PMID 31191822, 2019). "A partial explanation for the difficulty in identifying effective therapies for NF2 associated schwannomas and meningiomas is the difficulty in creating assay systems given that these are benign, slow growing tumors with relatively bland mutational backgrounds." (PMID 29897904, 2018). "Furthermore, NF2 mutations increase the risk of several tumors, such as ependymomas, meningiomas, and schwannomas." (PMID 30534000, 2018). "Mutations in the neurofibromatosis type 2 (NF2) gene are responsible for neurofibromatosis 2, a dominantly inherited familial cancer syndrome characterized by the formation of bilateral vestibular schwannomas and meningiomas." (PMID 29587439, 2018). "Importantly, meningiomas are the most common brain tumor worldwide and many sporadic meningiomas have somatic NF2 mutations." (PMID 29897904, 2018). "Hence, effective treatments for NF2-associated schwannomas and meningiomas are a major unmet medical need for both the broad population with sporadic forms of these tumors as well as for people with the rare syndrome of NF2." (PMID 29897904, 2018). "Furthermore, we also showed potential threshold value of PR and NF2 expression in which the risk of meningioma was significantly higher." (PMID 30687635, 2018). "Thus, there is an urgent need to identify anti-cancer drugs for the treatment of ependymomas, meningiomas, and schwannomas caused by NF2 gene mutations." (PMID 30534000, 2018). "Similarly, compared to group with highest 2 quartiles, those with the lowest 2 quartiles of NF2 expression also had significantly higher risk of meningioma (OR 4.23; 95% CI 1.85–9.67; P = 0.001)." (PMID 30687635, 2018). "These mutations are found in both NF2 and non-NF2 meningiomas." (PMID 30082628, 2018). "Finally, several studies have reported that approximately 60% of sporadic meningioma was associated with inactivation of the NF2 gene, which provided support to our study findings that low NF2 expression was related to increased risk of meningioma." (PMID 30687635, 2018). "Furthermore, up to 60% of patients with sporadic meningioma have allelic inactivation or loss of NF2." (PMID 30082628, 2018). "Loss of NF2 is found in approximately 50% of sporadic meningiomas." (PMID 28177878, 2017). "We found that primary atypical meningiomas were enriched for NF2 loss." (PMID 28195122, 2017). "We performed an in-depth genomic study of NF2-associated benign and atypical meningiomas." (PMID 28193203, 2017).
meningioma (continued). "The intracranial origin of a meningioma was also predicted by the underlying meningioma mutations, with non-NF2 mutant tumours being enriched in the neural crest derived anterior skull base region, while samples harbouring NF2 loss arose from the mesoderm-derived posterior regions." (PMID 28195122, 2017). "In addition, meningiomas with high OGN mRNA levels harbor more frequent NF2 or chr22 loss than those with low OGN mRNA levels, and OGN protein expression was higher in meningiomas with NF2 loss." (PMID 28923059, 2017). "Further investigation will be necessary to determine whether widespread copy number alterations, or NF2 mutations, tend to be earlier events in sporadic high-grade meningiomas." (PMID 28713588, 2017). "The NF2 deletion may be associated with alterations in cells leading to the fibroblastic subtype of meningioma." (PMID 29073243, 2017). "Radiation may generate genomic changes involving NF2 disruption and other changes that predispose to meningioma development over several decades." (PMID 28775249, 2017). "We show that the mutational background of primary atypical meningiomas to be comprised mainly of NF2 mutants, which frequently co-occur with either chromosomal instability or recurrent p.(Arg383Gln) or p.Arg386His mutations in SMARCB1 (co-occurrence P=1.2 × 10−7, Fisher’s exact test)." (PMID 28195122, 2017). "Currently, the somatic mutation landscape in NF2-associated meningiomas remains largely unexamined." (PMID 28193203, 2017). "This 4-hit/3-step model of tumorigenesis probably also holds true for other benign tumours observed in patients with SMARCB1-positive schwannomatosis, since biallelic inactivation of SMARCB1 and NF2 has been observed in a meningioma and leiomyoma of patients with germline SMARCB1 mutations." (PMID 27921248, 2017). "We first searched for known meningioma driver mutations in each sample, defining the distribution of benign versus atypical meningiomas in each of the molecular subgroups including NF2, TRAF7 (co-mutated with PI3K pathway or KLF4), Hedgehog and POLR2A mutant tumours." (PMID 28195122, 2017). "In addition, these cell lines also harbored known meningioma driver mutations in neurofibromin 2 (NF2) and TNF receptor-associated factor 7 (TRAF7)." (PMID 28552950, 2017). "In addition to assessing the efficacy of crizotinib against NF2-deficient schwannomas, the activity of crizotinib against other NF2-null tumors, such as meningiomas and mesotheliomas, should be evaluated." (PMID 27363027, 2016). "Collectively, these results suggest that Pak inhibitors might be useful agents in treating NF2-deficient meningiomas." (PMID 25596744, 2015). "Therefore, effective non-invasive therapies are much needed for NF2-associated meningiomas and vestibular schwannomas, as well as their sporadic counterparts commonly seen in the general population." (PMID 26219339, 2015). "Of note, several studies have reported different frequencies of NF2 mutation in meningiomas displaying distinct histopathological features; thus, alterations (e.g. monosomy) of chromosome 22q are more frequently observed in transitional and fibrous meningiomas than in the meningothelial variant." (PMID 25965831, 2015). "In particular, we demonstrate that independent activation of SGK1 and PAK1 may be partly responsible for the mTORC1 activation in NF2-deficient meningioma cells (model)." (PMID 26219339, 2015). "Employing a high-throughput shRNA kinome screening, here we have identified candidate kinases that may contribute to the observed mTORC1 activation in NF2-deficient meningioma cells." (PMID 26219339, 2015). "Because only 60% of sporadic meningiomas are associated with NF2 abnormalities, we also asked whether Pak inhibitors would affect Merlin-expressing meningioma cells." (PMID 25596744, 2015). "However, the mechanism by which merlin/NF2 loss in human arachnoidal and Schwann cells results in meningiomas and schwannomas remains poorly understood." (PMID 26219339, 2015).
meningioma (continued). "NF2-null CRISPR ACs recapitulate the signaling of NF2-deficient meningioma cells." (PMID 26219339, 2015). "Moreover, as in humans, Nf2 and Cdkn2ab loss cooperate to promote progression to histologically aggressive meningiomas." (PMID 26418719, 2015). "Loss of Merlin due to germline NF2 gene mutations leads to neurofibromatosis type 2 (NF2) disease, a nervous system cancer syndrome where patients primarily develop schwannomas and meningiomas." (PMID 26258444, 2015). "Accordingly, monosomy 22 is found in around half of meningioma cases, the great majority of NF2-associated meningiomas, as well as between 40-70% of sporadic meningiomas, displaying allelic losses (loss of heterozygosity, LOH) at the 22q12.2 chromosomal region, where the NF2 gene is encoded." (PMID 25965831, 2015). "Mutational inactivation of NF2 is found in 40–60% of sporadic meningiomas, but the molecular mechanisms underlying malignant changes of meningioma cells remain unclear." (PMID 25596744, 2015). "Besides NF2 mutations with loss of merlin expression, other protein 4.1 family members are also down regulated in meningioma." (PMID 25485306, 2014). "Moreover, animal studies showed that Nf2 loss in arachnoid cells is rate-limiting for meningioma formation, additional inactivation of p16Ink4a increases the frequency of meningioma." (PMID 25247996, 2014). "While inactivating mutations in NF2 have been described in 30 to 60% of sporadic meningiomas, recent studies have shown that non-NF2 meningiomas harbor activating mutations in SMO (L412F and W535L), AKT1 (E17K), and KLF4 (K409Q), as well as inactivating mutations of TRAF7." (PMID 25347344, 2014). "In line with this hypothesis, NF2- mutated meningiomas also showed a rather low incidence of LOH of the NF2 gene by SNP-arrays." (PMID 24171707, 2013). "NF2 gene mutations were found in 6/20 meningiomas studied (30%)." (PMID 24171707, 2013). "At the same time, we also review the literature reported so far on NF2 mutations in meningiomas." (PMID 24171707, 2013). "Since the earliest reports till 1994, more than 400 different NF2 mutations have been described in meningiomas; however, the precise significance of the NF2 gene status in sporadic meningiomas remains unclear." (PMID 24171707, 2013). "Interestingly, all NF2-mutated meningiomas corresponded to female patients (6/6 vs 11/14, p > 0.05) with a higher median age vs all other cases (73 vs 53 years; p = 0.03)." (PMID 24171707, 2013). "While the clinical manifestations of NF2 include central and peripheral nervous system tumors (nerve sheath tumors, meningiomas and ependymomas), cutaneous lesions, ocular pathology and peripheral neuropathy, the hallmark of NF2 is the development of bilateral cochleovestibular schwannomas (CVSs)." (PMID 23049959, 2012). "Like sporadic solitary meningiomas, sporadic multiple meningiomas may display somatic NF2 mutations, whereas familial multiple meningiomas do not." (PMID 19589153, 2009). "Even with this higher resolution array, the familial multiple meningioma tumors showed no ICS in any of the four tumors, supporting the view that familial multiple meningiomas are fundamentally different from sporadic multiple meningiomas both in terms of NF2 mutation and genomic profile." (PMID 19589153, 2009). "Thus, the synergy we observed between Nf2 and p16Ink4 mutations in meningioma development reflects the concomitant loss of two regulators of CDK4 activity resulting in cyclin D1 activation." (PMID 17924978, 2008).
meningioma (continued). "Mutations in the NF2 tumour suppressor gene underlie the familial cancer syndrome NF2, which is characterised by the development of tumours of the nervous system such as bilateral vestibular schwannomas and meningiomas." (PMID 17971776, 2008). "NF2 gene mutation frequencies in meningiomas of different histological subtypes." (PMID 17222329, 2007). "Meningiomas are closely associated with the genetic syndrome neurofibromatosis type-2 (NF2)." (PMID 17222329, 2007). "Meningiomas are common, mostly benign, tumours arising from leptomeningeal cells of the meninges, which frequently contain mutations in the neurofibromatosis type 2 (NF2) gene." (PMID 9310240, 1997). "However, the question was whether NF2 contributed to chromosome instability in meningiomas or whether NF2 loss was the consequence of an earlier event responsible for chromosome instability." (PMID 39991581, 2025). "Thus, detection for 22q loss and NF2 mutations might be required to grade meningioma in the next edition of WHO classification." (PMID 40815185, 2025). "Molecular modeling with DNA methylation, RNA expression, and copy number alterations may additionally advise on meningiomas that are likely to be radioresistant, including meningiomas within the proliferative molecular group or the NF2 loss of function during hypoxia." (PMID 40149634, 2025). "Furthermore, the embryonic origin is also associated with the fact that WHO grade 1 meningiomas, meningothelial subtype and non-NF2 tumours are mainly located at the skull base, whereas NF2 mutations, WHO grade 2/3 tumours and fibrous subtype are more commonly found in the convexities." (PMID 40359417, 2025). "Thus, we believe co-occurring mutations other than chromosome 1p loss, TERT mutation, CDKN2A/B loss can stratify NF2 mutated meningiomas, although a larger data set is required to confirm this hypothesis." (PMID 40562609, 2025). "The Cas9 mouse model of skull base meningioma generated with the Nf2 genetic defect and the combinational loss of P15Ink4b, P16Ink4a, and P19Arf could provide a new tool for investigating the pathogenesis of meningioma and the development of chemical interventions for this disease." (PMID 39996452, 2025). "The frequency of AKT and PIK3CA mutations in NF2 wild-type meningiomas highlights a prominent role of this pathway in the pathobiology of meningiomas in general, and it is conceivable that the activation of these pathways may contribute to tumorigenesis also in NF2 mutant tumors." (PMID 38571886, 2024). "Moreover, the mutation rate of NF2 was positively correlated with meningioma grade." (PMID 38879686, 2024). "However, molecular genetic studies have revealed that more than two-thirds of meningiomas carry deletions or mutations in the neurofibromatosis type 2 (NF-2) gene, which typically manifest as multiple tumors with a relatively poor prognosis, thus entailing an increased risk of mortality." (PMID 38611661, 2024). "Biallelic gene inactivation of NF2 resulting from chr22 monosomy and concurrent mutations in the remaining NF2 allele are characteristic alterations in multiple central and peripheral nervous system tumors in addition to meningioma including schwannomas and ependymomas." (PMID 39726707, 2024). "In NF2-related schwannomatosis, these two features—truncating mutation and N-terminal position—are associated with a clinically more severe phenotype with younger age at disease presentation and more frequent peripheral nerve tumors, spinal tumors and meningiomas (Whishart phenotype)." (PMID 38265489, 2024). "Dissecting the mechanisms of the PD‐L1‐driven tumorigenesis of NF2‐associated meningioma will help to improve our understanding of the mechanisms underlying tumor progression and could facilitate the further refinement of current therapies to improve the treatment of NF2 patients." (PMID 38828669, 2024).
meningioma (continued). "Dissecting the mechanisms of the PD‐L1‐driven tumorigenesis of NF2‐associated meningioma will help to improve our understanding of the mechanisms underlying tumor progression and could facilitate further refinement of current therapies to improve the treatment of NF2 patients." (PMID 38828669, 2024). "After PD‐L1 levels were downregulated by siPD‐L1 transfection in NF2‐associated meningioma cells, cell proliferation was significantly slowed, and the apoptosis rate was elevated, indicating that PD‐L1 may have important functions in promoting tumor formation and development." (PMID 38828669, 2024). "Interestingly, meningiomas present mutations in NF2 irrespectively of the histological grade." (PMID 38259646, 2023). "Thus, meningiomas can be dichotomized as NF2 (neurofibromatosis type 2) and non-NF2-mutated." (PMID 35879477, 2022). "NF2 patients frequently experience hearing loss and tinnitus as a result of VS growth; patients may also develop neuropathies, cutaneous features, cataracts, and schwannomas on other nerves, as well as meningiomas and ependymomas." (PMID 35332608, 2022). "Interestingly, our study suggested that, in sphenoid wing meningiomas, NF2 alteration/22q loss can significantly predict recurrence; however, additional CNV, methylome, and transcriptome analysis could allow for more accurate prognostic analysis." (PMID 35804955, 2022). "In this study, we found that in WHO grade 1 sphenoid wing meningiomas, NF2 alteration/22q loss is an independent factor that is associated with recurrence and that patients with these meningiomas may require close postoperative follow-up even if GTR is achieved." (PMID 35804955, 2022). "The patients with mutations in either of the NF genes may develop a wide variety of central and peripheral nervous system tumors, such as low- and high-grade astrocytomas, meningiomas, or schwannomas of cranial nerves, the last two being more frequently associated with NF2 deficiency." (PMID 35053664, 2022). "Lastly, 40% of NF2-mutated meningiomas express PD-L1 in the surrounding microenvironment, suggesting that the therapeutic role of checkpoint inhibitors is worth investigating in progressive/refractory meningiomas after the failure of surgery and/or radiation therapy." (PMID 35565385, 2022). "Notably, all grade 2 and 3 meningiomas had NF2 alterations and/or 22q loss." (PMID 35804955, 2022). "Loss-of-function mutations or deletions in NF2 cause neurofibromatosis type 2, a multiple tumour forming disease of the nervous system, characterized by the development of bilateral schwannomas, as well as meningiomas and ependymomas (Petrilli & Fernández-Valle, 2016)." (PMID 35975235, 2022). "Our radiomics model may aid the early identifcation of meningioma patients with NF2 mutation." (PMID 36267986, 2022). "Furthermore, we found two SMARCB1 mutations that co-occurred in NF2-mutant meningiomas." (PMID 35943573, 2022). "In addition to NF2-related meningiomas, NF2 mutations are found in ~50% of sporadic meningiomas." (PMID 34604034, 2021). "However, pathogenic variants in NF2 have been identified in 40–60% of sporadic meningiomas." (PMID 33262459, 2021). "Of note, only a quarter of all NF2 variants found (genomic position and bp change: 29604069, c.71_72insA; 29639100, c.A251C; 29642218, c.T380G; 29661212, c.683delG) had been previously identified in meningiomas, while the other 12 are reported here for the first time." (PMID 34868937, 2021). "Moreover, it lacks the NF2 mutation, which is the main driver event of malignant meningiomas." (PMID 34359639, 2021). "In an analysis of chromosome 22 in 44 sporadic meningiomas, researchers found that in 43 cases, all or part of the chromosome had been deleted, the majority of deletions occurring in the neurofibromatosis type 2 (NF2) region, suggesting that the mutation on NF2 leads to the occurrence of meningioma." (PMID 33042832, 2020).